EML4 (EMAP like 4)
Diseases named in the same sentence as EML4 in open-access papers (continued):
Sharing a sentence is not in itself a finding about the gene and the disease.
EML4 also shares sentences with these, for which no sentence is quoted: colorectal cancer (9 papers); chronic myelogenous leukemia (6); glioma (4); cervical cancer (3); Bladder cancer (2); colon cancer (2); metastatic cancer (2); thyroid tumor (2); acinar adenocarcinoma (1); acute megakaryoblastic leukemia (1); acute promyelocytic leukemia (1); Ad (1); adenocarcinoma in situ (1); anemia (1); Birt-Hogg-Dube syndrome (1); brain tumors (1); breast tumors (1); bronchioloalveolar carcinoma (1); cholelithiasis (1); colon (1); colorectal tumors (1); congenital mesoblastic nephroma (1); COVID-19 (1); diabetes (1); genetic disorders (1); gynecological cancers (1); head and neck cancer (1); hematological cancer (1); hematological malignancies (1); hepatoblastoma (1).
A further 28 diseases each share a sentence with EML4 in 1 paper.